VIM (vimentin)
Diseases named in the same sentence as VIM in open-access papers (continued):
Sharing a sentence is not in itself a finding about the gene and the disease.
cancer (continued). "Using an orthotopic xenograft-mouse model, we also observed that AEG-1 overexpression in human carcinoma cells led to the development of multiple lymph node metastases and elevated mesenchymal markers such as Vimentin, which is a characteristic of cells in EMT." (PMID 25880337, 2015). "Vimentin expression is an important indicator of EMT in carcinomas." (PMID 26095281, 2015). "Vimentin is a marker of mesenchymal cells; therefore, this finding suggests that the cancer cells in the MPP component may transform into mesenchymal cells." (PMID 25120667, 2014). "Several studies have shown that in cancer an increase of mesenchymal characteristics (N-cadherin and vimentin) and loss of epithelial characteristics (E-cadherin) via EMT is proportional with cancer progression, motility, invasiveness, drug resistance and metastasis." (PMID 25238234, 2014). "It is reported that p38 activation could upregulate E-cadherin and downregulate N-cadherin and vimentin in malignant HaCaT cells, which are key molecules mediating cancer cell migration or invasion." (PMID 24967005, 2014). "Vimentin is a well-recognized biomarker in epithelial to mesenchymal transition (EMT) and has been associated with metastasis, poorer prognosis, and cell motility in various types of cancer." (PMID 25478227, 2014). "In addition, increased expression of vimentin in various cancers is correlated with a poor prognosis." (PMID 24466036, 2014). "The rVP-1-mediated suppression of EMT as shown by induction of E-cadherin expression and reduction of vimentin could be reversed in cancer cells by transduction of pCOX-2 or pMIG-7." (PMID 25004182, 2014). "The results showed weak vimentin expression but strong E-cadherin expression in low IL-6-expressing cancer tissues, whereas strong vimentin expression but weak E-cadherin expression was observed in high IL-6-expressing cancer tissues." (PMID 24789104, 2014). "NIPBC-1 cell line which expresses punctate surface vimentin can be used as a model for creating nanoparticle- or antibody- cancer therapeutic agents capable of targeting vimentin in combination with other surface markers to prevent cancer metastasis as well as kill cancer stem cells." (PMID 24502646, 2014). "As a consequence, important cancer-related pathways are regulated, including Wnt- and Notch signaling, EMT associated genes (e.g., ZEB1/2, vimentin) and PTEN, contributing to IF-mediated inhibition of proliferation, invasion, migration and induction of apoptosis." (PMID 25322458, 2014). "In the present study, we found that 5-FU induced Huh7 cells to mesenchymal-like cancers in vitro and in vivo, by reducing E-cadherin and increasing vimentin expression, however, treatment with Sal plus 5-FU could reverse EMT induced by 5-FU." (PMID 24816638, 2014). "Vimentin, a mesenchymal marker, has been was observed in a few cancer cells." (PMID 25949790, 2014). "Thus, in agreement with previous data, we observed an increased expression of Vimentin in mesenchymal cells arising during cancer progression." (PMID 24878567, 2014). "Notably, we found that among infiltrating carcinomas, ICm showed a significantly higher number of vimentin-positive cells (293.0 ± 35.4) as compared with ICwm (162.1 ± 33.7)." (PMID 24758513, 2014). "Vimentin is an intermediate filament protein, with a key role in the epithelial to mesenchymal transition as well as cell invasion, and it is often upregulated during cancer progression." (PMID 23295955, 2013). "Since E-cadherin and Vimentin are bona fide cell invasion and metastasis mRNAs involved in the initial steps of cancer progression we further investigated their Fmrp-mediated regulation." (PMID 24092663, 2013). "This regulation may characterize the great majority of cancer cells, as demonstrated by the high correlation between the OVOL-TFs, ESRP1 and E-cad in addition to their inverse correlation with ZEB1 and vimentin in 917 cancer cell lines." (PMID 24124593, 2013).
cancer (continued). "Here, we determined whether WRE standardized to Withaferin A (sWRE) possesses anti-metastatic activity and whether it inhibits cancer motility via inhibition of vimentin and the EMT program." (PMID 24069380, 2013). "In addition to vimentin and TGF-β, the transmembrane glycoprotein CD44 has been implicated in cancer cell migration and invasion." (PMID 23295955, 2013). "Despite the clinical relevance, very little is known about vimentin regulation in cancer." (PMID 23295955, 2013). "Additionally, Src-mediated regulation of E-cadherin and vimentin has been reported in several cancers." (PMID 24023938, 2013). "The aberrant expression of vimentin and snail in epithelial tumors has been hypothesized to promote the migration and invasion of carcinoma cells." (PMID 24179501, 2013). "The PSC-induced cancer cell migration is associated with epithelial-mesenchymal transition in cancer cells as indicated by decreased expression of epithelial markers such as E-cadherin and increased expression of mesenchymal markers such as vimentin and Snail in cancer cells." (PMID 22973234, 2012). "One of the ways by which Snail can lead to cancer progression is through induction of epithelial-mesenchymal transition (EMT), which involves the loss of epithelial markers such as E-cadherin, and acquisition of mesenchymal markers such as vimentin." (PMID 22857708, 2012). "IHC examination with anti-E-cadherin and anti-vimentin antibodies further showed that cancer sites in metastatic lesions contain low E-cadherin/high vimentin levels, while conversely, normal tissue sites present with high E-cadherin/low vimentin expression levels." (PMID 22963683, 2012). "Vimentin overexpression induces tyrosine kinase expression and results in cancer cell migration." (PMID 23076115, 2012). "Although MPM cells are mesothelial in origin and express vimentin, and the fact that WA binds to tetrameric vimentin complex, and targets vimentin selectively in the cancer cells, we investigated whether WA targeted vimentin in MPM cells." (PMID 22912669, 2012). "Moreover, to confirm the appearance of the phenotype of DU145 differentiated cancer cells we analyzed the expression of the intermediate filament protein vimentin." (PMID 22328933, 2012). "At epithelial-stromal boundaries, single cell/strand migration of TβRIIfl/fl carcinoma cells was characterized by expression of α-smooth muscle actin and vimentin, while collective migration of TβRII KO carcinoma cells was identified by E-cadherin+/p120+/β-catenin+ clusters." (PMID 22748014, 2012). "CD44 and vimentin are upregulated during epithelial-mesenchymal transition (EMT) of cancer cells." (PMID 22216242, 2011). "However, the EMT phenotype expression was significantly lower (P = 0.037 for Twist and P = 0.004 for vimentin) in early stage cancer patients than in metastatic breast cancer patients." (PMID 21663619, 2011). "In addition to serving as a marker in EMT/MET, vimentin plays a versatile role in cancer cell motility." (PMID 21347296, 2011). "The expression of vimentin in cancer cells is believed to enhance migration and invasiveness." (PMID 21663619, 2011). "It is intriguing to speculate that these two populations actually represent meroclones or paraclones and that the CD44-High, Vimentin-High are holoclones that harbor stem-like cancer cells that has been reported for PC3 cells in culture." (PMID 24212937, 2011). "Cancer cell vimentin expression has also been found to influence treatment response in vitro." (PMID 21448168, 2011). "Interestingly, BC-M1 and BC-S1 cells co-express cytokeratin and vimentin consistent with an EMT-like invasive phenotype as well as other cancer stem cell characteristics." (PMID 21047409, 2010). "Furthermore, stem-like cancer cells exhibit EMT characteristics such as the loss of E-cadherin, increased expression of fibronectin and vimentin, and increased expression of mesenchymal transcription factors (Snail, Twist, and Slug)." (PMID 21067584, 2010).
cancer (continued). "Further support for this mechanism has recently been provided by other groups, describing involvement of withaferin A-dependent actin and vimentin microfilament aggregation in cancer cell apoptosis and suppression of angiogenesis via a direct thiol oxidation mechanism." (PMID 20438634, 2010). "In the present study, vimentin-positive cancers were more often found in younger women." (PMID 19695088, 2009). "The EMT of cancer cells is often induced by various transcription factors such as Snail, Twist and Slug, resulting in downregulation of epithelial markers such as E-cadherin and upregulation of mesenchymal markers such as vimentin." (PMID 19773759, 2009). "It is therefore reasonable to suggest that agents that reduce vimentin expression may have chemopreventive potential because of their ability to reduce cancer cell motility." (PMID 22792020, 2006). "However, vimentin-positively has repeatedly reported in various carcinomas and was interpreted as sign of an epithelial-mesenchymal transition, indicating an increased metastatic potential." (PMID 16412231, 2006). "Moreover, 23 cases showed high expression of vimentin in scattered cancer cells." (PMID 41496085, 2026). "Moreover, silencing miR-582-3p could reduce Vimentin expression by promoting E-cadherin expression through the Wnt/β-catenin pathway and inhibit cancer cell EMT." (PMID 40109856, 2025). "Thus, the role of vimentin in cancer progression is still unclear." (PMID 40332096, 2025). "Hence, increased expression of vimentin promotes cancer cell migration." (PMID 40443053, 2025). "As a result of the EMT transition the neo-epitopes that appear on vimentin are most likely due to epigenetic modifications since both normal and EDV are expressed by the same cancer cell which suggests the gene coding for vimentin is unchanged and not due to alternate splicing variants." (PMID 40051499, 2025). "Also, do these anti-vimentin antibodies have any implication in the anti-cancer immune response?" (PMID 40051499, 2025). "Resveratrol aids in reducing metastasis and EMT processes within cancer cells as it acts as an aberrant signalling pathway inhibitor, promotes the transcription of epithelial marker E‐cadherin, and reduces mesenchymal marker expression such as vimentin, N‐cadherin, and slug." (PMID 40888184, 2025). "Notably, the gradual changeover from keratin to vimentin intermediate-filament systems is a key trait of epithelial-mesenchymal transition, and the coexistence of both systems has been suggested as an indicator for aggressive cancer cells." (PMID 39026705, 2024). "Since plectin has been shown to be overexpressed in some cancers, it is possible that when cancer cells simultaneously overexpress both vimentin and plectin, they may have more VIFs accumulated at the perinuclear region and thereby tends to undergo nuclear dysmorphia." (PMID 39542246, 2024). "Finally, IWP-2 treatment could also attenuate the expressions of markers of EMT (enhanced E-cadherin and reduced vimentin levels) and cancer stemness (reduced CD44 and Oct4a but increased CD24 levels) as seen in the castration-relapse VCaP-NURR1 tumors." (PMID 38531859, 2024). "Similarly, whether LINC01559 regulates vimentin ubiquitination in other types of cancers and whether LINC01559 regulate ubiquitination of other proteins remain open questions." (PMID 38311781, 2024). "Importantly, VIM is known to be involved in metastasis in various cancer types." (PMID 38240752, 2024). "In cancer cells (LLC1) co-cultured with IDH2-deficient macrophages, the expression of E-cadherin, a cell adhesion protein, remained unchanged, whereas those of mesenchymal markers vimentin and fibronectin were decreased compared with their expressions in only cancer cells (LLC1)." (PMID 39256649, 2024).
cancer (continued). "Interestingly, yarrow-Sep inhibited key lipid metabolic targets in CRC cells extensively shown to be implicated in cancer dissemination and prognosis —SREBF1, FASN, ABCA1 and HMGCR— and epithelial to mesenchymal targets—CDH1, ATP1B1, CDH2 and Vimentin—augmenting cell adhesion." (PMID 38576446, 2024). "In addition, EMT is a crucial step of cancer cell migration and invasion, we focused on the possible associations between P4HA3 expression and classic EMT markers, such as Vimentin (VIM), TWIST1, Snail2 (SNAL2), Snail1 (SNAL1), Fibronectin1 (FN1), and N-cadherin (CDH2)." (PMID 39504328, 2024). "Thus, DKK4 expression in CRC cancer cells reduces the expression of β-catenin in stromal cells in cancer tissues, resulting in the transformation of fibroblasts to form stress fibre-containing fibroblasts and Vimentin+F-actin+MYH9+α-SMA+ myofibroblasts in cancer stromal tissues." (PMID 38519641, 2024). "Given the critical role of vimentin in cancer metastasis and the emerging understanding of its regulation at the cellular level, exploring the molecular mechanisms behind these processes, such as RNA modifications, becomes imperative for developing more effective cancer therapies." (PMID 38685125, 2024). "During EMT, cancer cells lose epithelial specific biomarkers (i.e., E-cadherin, cluster of differentiation CD44v variant isoform), while acquiring mesenchymal biomarkers (i.e., N-cadherin, fibronectin (FNT), vimentin (VIM), smooth muscle actin (α-SMA), β-catenin (CTNNB), CD44s standard isoform)." (PMID 38338903, 2024). "Additionally, processes related to cell growth and survival, as well as the production of specific molecules including the anti-stress response protein vimentin and the enzyme carbonic anhydrase, are all upregulated in cancer, while these processes and proteins are downregulated in AD." (PMID 38817545, 2024). "In addition, the researchers suggested that asiatic acid may play a role in inhibiting migration due to reduced expression of the mesenchymal markers N-cadherin, β-catenin, claudin-1, and vimentin, which are key in cancer cell migration and metastasis." (PMID 38610995, 2024). "The production of extracellular VIM and CK from immune and endothelial cells, which are both involved in carcinoma progression, could contribute to the higher levels of extracellular intermediate filaments in the serum of cancer patients relative to healthy donors." (PMID 39766058, 2024). "However, contradictory results about the effects of vimentin on cancer cell stiffness are reported." (PMID 37864030, 2023). "Interestingly, SUMOylation of vimentin favors cell proliferation and migration, which may increase the proliferation and invasiveness of cancer cells." (PMID 37833712, 2023). "Therefore, the aim of this study was to analyze the expression of Cxs and Panx1 in cancer and adjacent normal mucosa and vimentin, an indirect marker of epithelial–mesenchymal transition in LSCC, and to correlate the results with pathological parameters, pathological stage and clinical outcome." (PMID 36833374, 2023). "Initially, we expected that exPKM2 might be released from activated RA-FLSs, which exhibit the characteristics of cancer cells, including high metabolic activity, migration and invasion into surrounding tissue, since vimentin-expressing RA-FLSs showed the highest PKM2 expression." (PMID 35256696, 2022). "OCT4 alone or coexpressed with vimentin, reached statistical significance for OS and 5-year survival, respectively, after pairing with Arginase 1 (ARG1), suggesting that CSC and EMT may be linked, favouring cancer proliferation." (PMID 36358805, 2022). "Activation of EMT enables cancer cells to lose their epithelial property but acquire a mesenchymal, migratory phenotype through downregulating epithelial markers including ZO-1 and E-cadherin and upregulating mesenchymal markers such as N-cadherin and Vimentin." (PMID 35747815, 2022).
cancer (continued). "The concentration obtained in salivary ELISA for vimentin detection range from 2.33 to 3.34 ng/ml for healthy volunteer samples; for precancer samples, the concentration ranges from 4.5 to 5.02 ng/ml and for cancer samples, the concentration ranges from 4.82 to 1903.9 ng/ml." (PMID 35498535, 2022). "We postulated upon our data that vimentin is a potent factor to participate in maintaining the homeostasis of cell and tissue and, in doing so, protect colonic epithelial tissues from inflammation and cancer and further may facilitate intestinal repair." (PMID 35399505, 2022). "Furthermore, overexpression of vimentin led to decreased expression of E-cadherin, while knockdown resulted in an increased level of a differentiation-specific marker involucrin, suggesting a role of vimentin in maintaining the dedifferentiated state of cells during cancer progression." (PMID 35207438, 2022). "Consequently, studies provided vimentin as an available targeted cancer therapy." (PMID 35081125, 2022). "Moreover, the MTAP‐ and PRMT5‐mediated sDMA modification negatively regulates the stability of vimentin protein via proteasomal degradation, as evidenced by the observations from two independent cohorts, Taiwan Cancer Moonshot proteogenomic data and tissue microarray IHC staining data." (PMID 35766227, 2022). "Overexpression of vimentin in ameboid cancer cells contributes to cell resilience by limiting deformations in response to fast contractions, indicating that cell type-specific expression levels of vimentin endow cells with a broad range of mechanical properties." (PMID 35359446, 2022). "In addition, the vimentin protein expression has been validated in saliva samples obtained from precancer and cancer patients and found to be significantly upregulated when compared to normal samples, proving its role as a useful biomarker for the early detection and disease monitoring." (PMID 35498535, 2022). "Previous work indicated that members of the OSBP family could regulate the subcellular distribution of ORP–VAPA complexes and their impacts on organelle structure and consequently affect malignant tumor cell invasion and metastasis, potentially via changes in vimentin distribution." (PMID 35127474, 2021). "Our study suggests that vimentin promotes exosome release, and small-molecule compounds that target vimentin are able to both block cancer exosome release and reduce cancer cell motility, and therefore could have potential applications for inhibiting cancer invasive growth." (PMID 34305581, 2021). "Thus, we aimed here to investigate the effects of vimentin on cancer cells in particular." (PMID 34299089, 2021). "Thus, collapse of vimentin architecture and subsequent modification of its assembly/disassembly may be the mechanism underlying IGFBP-3-mediated regulation of cancer cell migration and invasion." (PMID 33801272, 2021). "Moreover, MTORC1 and mTORC2 were shown to be modulators of EMT in cancer, while the silencing mTORC1 and mTORC2 resulted in an increase in E-cadherin and decrease in N-cadherin, vimentin, and snail, and other characteristics of mesenchymal to epithelial transition (MET)." (PMID 33530617, 2021). "Therefore, targeting vimentin is a promising approach for anti-cancer therapy." (PMID 33757532, 2021). "This has suggested that vimentin could be targeted to prevent cancer cell motility." (PMID 36046434, 2021). "In this type, cancer cells resemble rhabdomyoblasts, which are small and round with hyperchromatic nuclei and are immunohistochemically characterized by the increased expression of vimentin, epithelial membrane antigen, and cytokeratins, as well as by the loss of BRG1 protein expression." (PMID 33907931, 2021). "Therefore, it is plausible to say that IGFBP-3 might regulate the motility of cancer cells by interfering with the interaction between vimentin and Akt." (PMID 33801272, 2021).